IL26 (interleukin 26)
Diseases named in the same sentence as IL26 in open-access papers (continued):
Sharing a sentence is not in itself a finding about the gene and the disease.
uterine fibroids (1 paper, 2025). "The findings indicate that STAT-3 and IL-26 are significantly increased in uterine leiomyoma tissue, and that this increase may be associated with various cellular mechanisms that promote tumor growth." (PMID 40943781, 2025). "In future studies, pharmacologically targeting cytokine signaling pathways, such as STAT-3 or IL-26, may offer a potential treatment option to control the growth of uterine fibroids, which are very common in women of reproductive age." (PMID 40943781, 2025). "Therefore, prospective studies are needed to better understand the expression and effects of IL-26 in uterine fibroids." (PMID 40943781, 2025). "However, there is limited information on the expression and effects of IL-26 in uterine fibroids in the existing literature." (PMID 40943781, 2025). "In this study, we examined the levels of STAT-3 and IL-26 expression in samples obtained from patients with leiomyoma uteri and patients who underwent hysterectomy for benign reasons and evaluated the possible role of this transcription factor in the pathogenesis of uterine fibroids." (PMID 40943781, 2025).
tumor (24 papers, 2018 to 2025). "When analyzing the T cell infiltrates, we found an association of a tumor-promoting subpopulation, characterized by the expression of interleukin (IL) 21 and IL26, with high ADC values." (PMID 31948053, 2020). "The aim of the current study is to investigate the role of IL21 and IL26 on tumor progression as well as their association with changes in the tumor microarchitecture of PDAC that can be detected in vivo by DW-MRI." (PMID 31948053, 2020). "In terms of its mechanism of action, IL-26 stimulates IL-22-producing cells, which subsequently suppress cytotoxic T-cell function and facilitate tumor progression through activation of anti-apoptotic signaling pathways." (PMID 41515435, 2025). "Subsequent analysis revealed a robust positive correlation among the expressions of IL-22, IL-26, and IL-17A, with their corresponding receptors were notably elevated in the tumor samples." (PMID 40452847, 2025). "Our data indicate that Tc17 cells highly express a range of cytokines, notably IL-16, IL-17A, IL-17F, IL-22, and IL-26, and it is these five cytokines for which receptors are also highly expressed in tumor cells." (PMID 40452847, 2025). "This is a biologically relevant observation, as IL-26 is known to induce inflammation, promote tumor growth, and enhance angiogenesis." (PMID 41515435, 2025). "Recently, IL-26 has gained attention for its involvement in cancer development, with elevated levels observed in various tumor tissues." (PMID 40806452, 2025). "The tumor microenvironment (TME) significantly modulates the impact of IL-26 on tumor formation and progression." (PMID 41516201, 2025). "In recent years, a growing body of research has investigated the role of IL-26 in the initiation and promotion of malignant transformation, as well as in tumor invasion and metastasis." (PMID 41516201, 2025). "We observed that IL-16, IL-17, IL-22, and IL-26 are specifically expressed in Tc17 cells, and their corresponding receptors are also highly expressed in tumor cells." (PMID 40452847, 2025). "Collectively, these findings reveal that IL17A and IL26 not only individually enhance malignant phenotypes of GC cells but also act synergistically to potentiate tumor progression." (PMID 40452847, 2025). "Subsequently, the Tc17-derived IL-17A and IL-26 further promoted tumor progression, as validated by CCK-8, wound-healing, and transwell assays." (PMID 41516201, 2025). "The markedly higher IL-26 levels in HCC patients at least partially originate from macrophages residing in the tumor mass, as suggested by a significant overlap between IL-26 and CD68 immunostaining." (PMID 41516201, 2025). "IL-26 was also distinctly detected in tumor-infiltrating lymphocytes (TILs) of not only TNBC but also HER2-positive and Luminal breast tumors." (PMID 40806452, 2025). "Increased numbers of IL21+ and IL26+ T cells have also been seen in PDAC and associate with an impaired clinical outcome, potentially through direct engagement with IL21R on tumor cells." (PMID 36689623, 2023). "Our data showed that the expression of IL26 was significantly decreased in tumor tissue compared with corresponding normal control, and IL26 expression was significantly correlated with the prognosis of HNSCC." (PMID 35902909, 2022). "Our data showed that gefitinib-treated TNBC cells exhibited enhanced production of proinflammatory cytokines/chemokines such as IL-6, IL-8, and CXCL2, hence increasing the number of tumor-infiltrating immune cells including IL-26-producing cells in the TME." (PMID 34021125, 2021). "In the TME, the presence of CAFs and their secretion of chemokines and cytokines such as CCL2, CCL5, CCL17, IL-1, IL-6, IL-13, and IL-26 can favor a tumor-promoting Th2 and Th17 immune response, at the expense of tumor-protective Th1 responses." (PMID 34663337, 2021).
tumor (continued). "To identify a key regulator of tumor growth downstream of IL-26/EphA3 interaction in TNBC, we performed pathway analysis by DNA microarray of HCC70 cells treated with IL-26 and gefitinib." (PMID 34021125, 2021). "The presence of IL10RB/IL20RA in tissue was associated with shorter survival time, compatible with the notion that IL26 signaling per se contributes to tumor progression." (PMID 31948053, 2020). "In conclusion, we report the infiltration of tumor-promoting Th17-like cells, expressing their related cytokines IL21 and IL26 and their association with particularly aggressive disease." (PMID 31948053, 2020). "CD4+ helper T lymphocytes react to CAF secretion of CCL2, CCL5, and CCL17 along with polarizing cytokines IL-1, IL-6, IL-13, and IL-26 by switching from an anti-tumor TH1 response to a pro-tumor TH2 and TH17 response." (PMID 31058816, 2019). "Second, antibodies or small molecule inhibitors targeting IL-17A and IL-26 secreted by Tc17 cells may effectively block their tumor-promoting actions." (PMID 40452847, 2025). "Similarly, wound healing assays demonstrated that IL17A and IL26 individually promoted the migratory capacity of tumor cells, while combined treatment elicited the highest migration rate." (PMID 40452847, 2025). "In addition, mice vaccination with an adenoviral agent to immunologically target IL-26 reduced tumor growth and prolonged survival, suggesting it as an actionable therapeutic target to suppress inflammation and inhibit TNBC progression." (PMID 40806452, 2025). "And in turn, Tc17 cells may promote tumor progression by secreting IL-17A and IL-26, as functionally corroborated by CCK-8 Assay, wound healing, and transwell assay in vitro." (PMID 40452847, 2025). "Interestingly, we found their receptors, IL17RA/IL17RC for IL17A/IL17F, IL10RB/IL22RA1 for IL22, and IL20RA/IL10RB for IL26, were upregulated in tumor cell than in normal epithelial cells." (PMID 35999201, 2022). "Since the gene encoding IL-26 is absent in mice, we utilized human IL-26 transgenic (hIL-26Tg) mice as a tumor-bearing murine model to characterize the role of IL-26 in the differential effect of EGFR-TKI in human and mice and to confirm our in vitro findings." (PMID 34021125, 2021). "In our experimental setting, we could demonstrate and increased tumor colony formation upon long term incubation with IL21 and IL26, and thus an increased ability to form more and larger vital tumor cell clusters." (PMID 31948053, 2020). "It is likely that the extracellular DNA carrier capacity of IL-26 and/or its aberrant expression may drive the chronicity of inflammation and hence tumor progression." (PMID 31936322, 2020). "In summary, our data showed an association of IL21+ and IL26+ immune cell infiltration, increased ADC, and aggressive tumor disease, most likely due to the activation of the key cancer signaling pathways ERK1/2 and STAT3 and formation of tumor colonies." (PMID 31948053, 2020). "In turn, Tc17 cells may promote tumor progression by secreting IL-17A and IL-26." (PMID 40452847, 2025). "Furthermore, IL-26 is known to induce cells that produce IL-22, potentially reducing the cytotoxic T cell function through the activation of anti-apoptotic proteins, thus fostering tumor growth." (PMID 40452847, 2025). "Taken together, these findings indicate that interaction of IL-26 and EphA3 induces increased phosphorylation of AKT and JNK not only in murine TNBC but also in human TNBC, hence activating the EGFR-TKI-associated bypass pathway to result subsequently in tumor growth." (PMID 34021125, 2021). "In summary, our findings establish the IL26 and CX3CL1 signaling as a critical mediator of BM-CAF-induced tumor progression and therapy resistance in NSCLC BM, suggesting a potential therapeutic strategy for this challenging disease." (PMID 41029793, 2025).
tumor (continued). "Once in close proximity to the tumor cells, these Tc17 cells engage in a reciprocal signaling cascade, secreting interleukins (IL-16, IL17, IL-22, and IL-26), thereby forming a vicious cycle that promotes the progression of tumor cells." (PMID 40452847, 2025). "Promote tumor progression through IL17, IL22 and IL26 signaling or Tc17 (IL-17CD8 T cells) differentiation into exhausted T cells." (PMID 39906741, 2024). "While, the paired analysis showed that expression of IL26, IL17F, KLRB1, CD40LG, JCHAIN, and NFKBIZ were significantly lower in the tumor group, compared with normal tissues." (PMID 35902909, 2022). "In Epstein–Barr virus (EBV)-infected nasopharyngeal epithelial cells, the responses to interleukin (IL)-26-induced signal transducer and activator of transcription 3 (STAT3) activation were enhanced to promote tumor progression." (PMID 36551991, 2022). "attempted to introduce new therapies based on Th17 lymphocytes which produce IL-17A, IL-17F, IL-21, IL-22, IL-26, IL-6, TNF-α and suppress tumour progression through enhanced antitumor immunity in OC." (PMID 34621670, 2021). "After log-transformation, the following biomarkers displayed a normal distribution and statistically significant differences in tumor vs. control (in alphabetical order): APRIL, BAFF, CA19-9, pERK, IL-1β, IL-1RA, IFN-β, IL-26, MMP-2, and TWEAK." (PMID 33846436, 2021). "Our study revealed that interaction of IL-26 and EphA3 in TNBC activates AKT and JNK, leading to tumor proliferation by inhibiting EGFR-TKI-provoked PERK-eIF2α-DDIT3 pathway and ER stress-associated cell death." (PMID 34021125, 2021). "These cells produce various tumor-promoting cytokines, including TNF-α, IL10, and IL17A, and also the less well-studied cytokines such as IL21 and IL26." (PMID 31948053, 2020). "This study is now focused on tumor-infiltrating T cells, particularly those expressing IL21 and IL26, as these are major cytokines produced by tumor-promoting Th-17-like cells." (PMID 31948053, 2020). "In the TME, the presence of CAFs and their secretion of CCL2, CCL5, and CCL17 as well as the polarizing cytokines IL-1, IL-6, IL-13, and IL-26 can favor a tumor promoting TH2 and TH17 immune response, as the expense of tumor protective TH1 response." (PMID 29545811, 2018). "In gastric cancer, IL17 cells may promote tumor progression through IL17, IL22 and IL26 signaling or Tc17 (IL-17CD8 T cells) differentiation into exhausted T cells." (PMID 39906741, 2024). "Our results indicate that IL17+ cells may promote tumor progression through IL17, IL22, and IL26 signaling, highlighting the possibility of targeting IL17+ cells and associated signaling pathways as a therapeutic strategy to treat GC." (PMID 35999201, 2022). "In the current study, exogenous IL-26 induced dephosphorylation of EphA3 in TNBC, followed by phosphorylation of AKT and JNK leading to suppression of ER stress signaling, resulting in enhanced tumor growth of EGFR-TKI-resistant TNBC." (PMID 34021125, 2021). "IL-26 induced dephosphorylation and downmodulation of EphA3 in TNBC, which resulted in increased phosphorylation of AKT and JNK against EGFR-TKI-induced endoplasmic reticulum (ER) stress, leading to tumor growth." (PMID 34021125, 2021). "Of note, the numbers of IL21 or IL26 positive T cells were not significantly correlated to tumor size, histological grading, or lymph node positivity (p ≥ 0.2510)." (PMID 31948053, 2020). "Tc17 cells may stimulate tumor development via IL-17, IL-22, and IL-26, while non-cytotoxic Tc17 cells may become cytotoxic in the presence of IL-12, having a deadly impact on tumor cells." (PMID 39676857, 2024). "Thus, we hypothesized that IL17+ T cells in GC could promote tumor growth via IL17, IL22, and IL26 signaling." (PMID 35999201, 2022).
tumor (continued). "Despite the EphA3-related molecular alterations associated with IL-26 alone, treatment with IL-26 alone did not alter TNBC growth; rather, the effect of IL-26 on TNBC tumor growth was seen in the setting of EGFR-TKI exposure with an increased ER stress response." (PMID 34021125, 2021).
infection (16 papers, 2013 to 2025). The state of being infected such as from the introduction of a foreign agent such as serum, vaccine, antigenic substance or organism. "Infection of larvae with E. tarda confirmed intrinsic bactericidal activity of IL-26, with il26−/− larvae showing an increased bacterial load and infection-associated mortality." (PMID 41125849, 2025). "Live imaging revealed that E. tarda accumulated primarily in the mid and posterior gut at 3 days post infection (dpi) in both WT and il26-/- larvae." (PMID 41125850, 2025). "We found that the presence of IL-26 improves macrophage survival by decreasing the infection rate of Mtb." (PMID 33057074, 2020). "(B) Peritoneal mouse macrophages were pretreated with recombinant human IL-26 (100 ng/mL) for 6 h and then infected with live E. coli (multiplicity of infection, 10)." (PMID 31464651, 2019). "(B) Peritoneal mouse neutrophils were pretreated with recombinant human IL-26 (100 ng/mL) for 6 h and then infected with live E. coli (multiplicity of infection, 100)." (PMID 31464651, 2019). "More precisely, a pre-incubation of vesicular stomatitis virus (VSV) with IL-26 increases the rate of infection of the epithelial cell line Colo-205, whereas an opposite effect is observed with the human Cytomegalovirus (CMV)." (PMID 30809226, 2019). "IL-26 displays differential abilities in modulating the rate of epithelial and fibroblast cell infections by enveloped viruses." (PMID 27337042, 2016). "After pre-incubation with recombinant IL-26 and at low multiplicity of infection, VSV showed strongly enhanced infection and replication rates as measured for infectivity, for transcript levels, and for protein expression." (PMID 23875025, 2013). "Since already early time points after infection yielded obvious IL-26-effects, the first 4 h after VSV infection were examined more closely." (PMID 23875025, 2013). "From 4–12 h post infection, IL-26 increased the virus titers about ten-fold in contrast to medium- or GST-treated virus." (PMID 23875025, 2013). "Independently of the IL-20R1 expression status, all cell lines showed increased infection rates after IL-26 pre-incubation of target cells at variable extent as analyzed by flow cytometry." (PMID 23875025, 2013). "The virus-encoded GFP transcription in Colo-205 after VSV infection was analyzed from 1–4 h post infection by quantitative RT-PCR in order to determine the very early time course of the IL-26-dependent effects on VSV replication." (PMID 23875025, 2013). "This indicated that IL-26-treated VSV was more successful in infection already after 2 h and argues in favour that VSV attachment and entry into target cells are facilitated by IL-26." (PMID 23875025, 2013). "Here, we describe the IL-26 effects on the infection of culture cells with recombinant vesicular stomatitis virus (VSV), human cytomegalovirus (HCMV), and herpes simplex virus type 1 (HSV-1) expressing green fluorescent protein." (PMID 23875025, 2013). "After nickel-chelate chromatography, recombinant GST protein was used as control protein in parallel to IL-26 in infection experiments." (PMID 23875025, 2013). "This indicates that the number of infected target cells after IL-26-treatment of VSV particles is substantially higher in the very early infection phase, presumably by facilitated VSV attachment and entry into target cells." (PMID 23875025, 2013). "il26-/- larvae exhibited higher mortality compared to WT upon infection." (PMID 41125850, 2025). "To know whether this infection model induces il26 expression, we quantified mRNA levels in dissected WT larval guts at 1 and 3 dpi." (PMID 41125850, 2025). "Similarly, il26-/- guts showed higher cytokine expression levels upon infection compared to uninfected il26-/- controls." (PMID 41125850, 2025). "Finally, to characterize the immune response in the gut of il26-/- upon infection, we measured the expression levels of several cytokines in WT and il26-/- larval guts at 3 dpi." (PMID 41125850, 2025).